HSP90AA1 (heat shock protein 90 alpha family class A member 1)
Diseases named in the same sentence as HSP90AA1 in open-access papers (continued):
Sharing a sentence is not in itself a finding about the gene and the disease.
lung adenocarcinoma (7 papers, 2017 to 2025). A carcinoma that arises from the lung and is characterized by the presence of malignant glandular epithelial cells. "For other types of cells in lung adenocarcinoma tissues, the expression of HSP90AA1 elevated due to the complexity of tumor tissue and alterations in the tumor microenvironment." (PMID 37587188, 2023). "The findings demonstrated a significant increase in the expression of the HSP90AA1 protein product in lung adenocarcinoma tissues compared to the levels observed in normal tissues, respectively." (PMID 37587188, 2023). "Consistent with this, high expression of HSP90AA1 and HSP90AB1 was significantly correlated with poorer prognosis of patients suffering from lung adenocarcinoma." (PMID 36982267, 2023). "RPL3, HSP90AA1, ATAD2, and PIAS1 as well as USP25, which is targeted by miR-200b, miR-200c, and miR-429, may be the potential targets of HPD in lung adenocarcinoma." (PMID 30717818, 2019). "RPL3, HSP90AA1, ATAD2, as well as PIAS1 and USP25, which is targeted by miR-200b, miR-200c, and miR-429 may show correlations with the sensibilization effect of HPD in lung adenocarcinoma." (PMID 30717818, 2019). "Overall, our data reveal an important physiological role for S100-A15 in comprehending the proliferative, metastatic, and invasive properties of lung adenocarcinoma which may be orchestrated by CTNNB1 with the involvement of ZEB1, CDC42, HSP90AA1, PCNA and BST2." (PMID 28498804, 2017).
Obesity (7 papers, 2018 to 2025). Accumulation of substantial excess body fat. "The NF-κB target genes IRF1, STAT1, JUN, HSP90AA1, FOS, and EGR1, were enriched in the pathway of Glucocorticoid receptor regulatory network and homeostasis pointing towards their critical role in obesity." (PMID 31013288, 2019). "In these studies mRNA expression of Hsp90ab1, Hsp90aa1, Hsp90b1, and TRAP1 were assessed from skeletal muscles of mice fed a high fat diet (diet-induced obesity, DIO) and compared to lean counterparts." (PMID 29434648, 2018). "The most involved anti-obesity proteins include EGFR, STAT3, JUN, GSK3B, PPARG, and HSP90AA1." (PMID 38674532, 2024).
cervical carcinoma (6 papers, 2014 to 2025). A carcinoma arising from either the exocervical squamous epithelium or the endocervical glandular epithelium. "We identified seven genes consistent with prognosis and nine genes consistent with the process of cervical cancer formation, among which ELAVL1 and HSP90AA1 are involved in protein inter-righting." (PMID 35965520, 2022). "Although the identified immune-related hub genes (HSP90AA1, CTNNB1, NPM1, HSPA5, and HIF1A) were significantly downregulated in HPV-positive cervical cancer, none of them demonstrated a statistically significant correlation with overall survival in the TCGA-CESC cohort." (PMID 41465546, 2025).
glioma (6 papers, 2019 to 2024). A benign or malignant brain and spinal cord tumor that arises from glial cells (astrocytes, oligodendrocytes, ependymal cells). "The mRNA expression levels of AKT1 and MAPK1 were relatively high in glioma, while those of RXRα, ESR1, and HSP90AA1 were relatively low." (PMID 38835342, 2024). "The analysis revealed that the top five genes affected by isocuB in glioma were RXRα, AKT1, ESR1, MAPK1, and HSP90AA1." (PMID 38835342, 2024). "The potential top five genes of the anti-glioma effect of isocuB were identified by network pharmacology as RXRα, AKT1, ESR1, MAPK1, and HSP90AA1." (PMID 38835342, 2024). "consistently showed that PTPRN interacts with HSP90AA1 to activate PI3K/AKT signaling pathway and promote the proliferation and metastasis of high-grade gliomas." (PMID 36814929, 2023). "Glioma stem cells (GSCs) are a vital element contributing to treatment resistance in GBM, and multiple investigations have shown that HSP90AA1 (Heat Shock Protein 90 Alpha Family Class A Member 1) inhibitors successfully induce cell death in GSCs." (PMID 36422293, 2022). "Interestingly, PTPRN is highly expressed in patients with high-grade glioma, which activates the PI3K/AKT pathway by interacting with HSP90AA1 to promote cell proliferation and metastasis." (PMID 35741647, 2022).
leukemia (6 papers, 2017 to 2025). A malignant (clonal) hematologic disorder, involving hematopoietic stem cells and characterized by the presence of primitive or atypical myeloid or lymphoid cells in the bone marrow and the blood. "In limited studies, stilbenes were proved to be highly related to targets of leukemia treatments, for example, pterostilbene, a 3′, 5′-dimethoxy-resveratrol interacted with 25 targets, including MAPK14, CDK2, and HSP90AA1, which are highly related to leukemia." (PMID 32104190, 2020). "Notably, for the drug Flavopiridol hydrochloride (CID: 5687969), investigated for use/treatment in leukemia (lymphoid), the predicted target HSP90AA1 (Entrez ID: 3320) is a neighbor to eight known targets in the PPI network (Entrez IDs: 983, 1017, 1019, 1020, 1021, 1022, 1025, 1956)." (PMID 30255785, 2018).
pancreatic cancer (6 papers, 2019 to 2025). "High expression levels of HSP90AA1 and HSP90AB1 (associated with a low MZF1 expression scenario) were significantly correlated with poorer prognosis of patients suffering from pancreatic cancer." (PMID 36982267, 2023).
Sepsis (6 papers, 2021 to 2025). Sepsis is defined as life-threatening organ dysfunction caused by a dysregulated host response to infection. "HSP90AA1 functions as a core danger-associated molecular pattern in sepsis." (PMID 40808684, 2025). "The analysis showed that NOS3, SIRT1, HSP90AA1, MMP9, MMP2, PTPRC, and TLR2 were associated with multiple organ damage in sepsis." (PMID 36406124, 2022). "Differential analysis of SIRT1, TLR2, and HSP90AA1 in the sepsis liver injury-control group (SLi-C), p-value were all <0.05, and differential expression." (PMID 36406124, 2022). "Patients with sepsis-related ARDS had reduced levels of HSP90AA1." (PMID 38871699, 2024). "The genes co-regulated by Acu-exo and sepsis were derived from multiple organs and systems, their interacting genes(HSP90AA1, GRB2, EGFR etc.)and signaling pathways(MAPK, TNF, JAK-STAT etc.)were involved in inflammation, immune regulation, metabolism, and cell proliferation and apoptosis." (PMID 37635258, 2023). "Overall, the findings of this study suggested that Hsp90aa1 knockdown is a potential novel candidate target for ameliorating lung epithelial cell injury, which may further novel insights into the etiopathogenesis of sepsis-induced acute lung injury." (PMID 39220589, 2024). "Differential analysis of HSP90AA1, MMP2, and MMP9 in the sepsis spleen injury-control group (SSp-C) showed that the p-value were all <0.05, indicating differential expression." (PMID 36406124, 2022). "Differential analysis of NOS3, MMP2, HSP90AA1, and SIRT1 in the sepsis kidney injury-control group (SKi-C) showed that the p-value were all <0.05, indicating differential expression." (PMID 36406124, 2022). "Our PPI network analysis further unveils several key regulators like TOP2A, PAICS, HSPE1, HSP90AA1 and ACACA in the central hubs of dysregulated gene network in sepsis-induced ARDS." (PMID 33904373, 2021).
Hypertension (5 papers, 2017 to 2025). The presence of chronic increased pressure in the systemic arterial system. "Although the role of HSP90AA1 has not been implicated in the pathogenesis of hypertension, it has been identified as a hub gene in multiple bioinformatics studies exploring gene expression profiles in pulmonary arterial hypertension." (PMID 39592923, 2024). "Moreover, the effect of Tianma on correcting the function and activity of Tpi1, Ppia, Ncam1, Uchl1, Septin-2 and Hsp90aa1 proteins, provided conclusive evidence for Tianma in the treatment of seizures, hypertension and headaches." (PMID 29262557, 2017). "Our analyses showed that TNF, HSP90AA1, NFKB1, PPARG, SIRT1, PTGS2, and RELA might be α-MG’s potential therapeutic targets for hypertension, laying groundwork for further investigation into its pharmacological mechanisms and clinical uses." (PMID 39592923, 2024). "The results indicate that in the Ang II-induced hypertension group, the expression levels of TNF, NFKB1, MAPK3, PTGS2, and RELA were markedly elevated compared to the control group, while the expression levels of HSP90AA1, HSP90AB1, PPARG, SIRT1, MAPK1, and PRKCA were significantly decreased." (PMID 39592923, 2024).
male infertility (5 papers, 2021 to 2025). The inability of the male to effect fertilization of an ovum after a specified period of unprotected intercourse. "Targeted disruption of the HSP90AA1 gene can lead to male infertility in mice." (PMID 37286946, 2023).
non-small cell lung carcinoma (5 papers, 2019 to 2023). A group of at least three distinct histological types of lung cancer, including non-small cell squamous cell carcinoma, adenocarcinoma, and large cell carcinoma. "According to another study, CDK1 and HSP90AA1 were also found to be common in their analysis, suggesting that CDK1 and HSP90AA1 play an important role in the regulation of non-small cell lung cancer." (PMID 37764733, 2023). "HSP90AA1 is a gene that promotes squamous cell lung cancer progression and has an important regulatory role in non-small cell lung cancer." (PMID 37347115, 2023). "In conclusion, our study identified multiple important genes, including CDK1 and HSP90AA1 which showed differential expression in non-small cell lung cancer patients compared to control through DEG analysis and network building." (PMID 35330393, 2022). "We found that two genes, CDK1 and HSP90AA1, were common in the analysis suggesting a significant regulatory role of CDK1 and HSP90AA1 in non-small cell lung cancer." (PMID 35330393, 2022). "LncRNA KCNQ1OT1 facilitates the progression of non-small-cell lung carcinoma via modulating miRNA-27b-3p/HSP90AA1 axis." (PMID 31001325, 2019). "This suggests significant regulatory roles of CDK1 and HSP90AA1 in non-small cell lung cancer." (PMID 35330393, 2022).
squamous cell lung carcinoma (5 papers, 2020 to 2023). A carcinoma arising from squamous bronchial epithelial cells. "It has been reported that HSP90AA1, a chronic obstructive pulmonary disease-related gene, can promote the progression of squamous cell lung cancer." (PMID 36765042, 2023).
head and neck squamous cell carcinoma (4 papers, 2021 to 2023). A squamous cell carcinoma that arises from any of the following anatomic sites: lip and oral cavity, nasal cavity, paranasal sinuses, pharynx, larynx, and salivary glands. "Indeed, HSP90AA1 is highly coexpressed with HSPH1 during head and neck squamous cell carcinoma (HNSCC), which means that these factors could be either prognostic biomarkers or potential clinical targets." (PMID 36766730, 2023).
Infertility (4 papers, 2015 to 2026). "Screening via the STRING platform and Cytoscape 3.10.1 software yielded four core targets for ATBC-induced infertility-HSP90AA1, PIK3CA, CASP3, HRAS-and four core targets for icariin treatment-IL6, TNF, STAT3, and INS." (PMID 41898778, 2026). "In fact, overexpression of 5 HSPs and 5 CCTs is noticed in High ROS infertile group whereas only one HSP each, HSPA1L and HSP90AA1 was induced in Medium and Low ROS group respectively." (PMID 26321892, 2015).
Insulin resistance (4 papers, 2020 to 2025). Increased resistance towards insulin, that is, diminished effectiveness of insulin in reducing blood glucose levels. "Genes with higher degree including VEGFA, PTGS2, JUN, MAPK8, and HSP90AA1 are hub genes of TwHF against DKD, which are involved in inflammation, insulin resistance, and lipid homeostasis." (PMID 33274236, 2020).
liver disease (4 papers, 2021 to 2025). "The co-targets are closely related to liver diseases, and in the degree order, the top four included heat shock protein 90AA1 (HSP90AA1), peroxisome proliferator-activated receptor G (PPARG), heat shock protein 90AB1 (HSP90AB1), and signal transduction and transcriptional activator 1 (STAT1)." (PMID 33510287, 2021).
lymphoma (4 papers, 2008 to 2025). A malignant (clonal) proliferation of B- lymphocytes or T- lymphocytes which involves the lymph nodes, bone marrow and/or extranodal sites. "The effects of artesunate-induce inhibition on the expression of Hsp90aa1, Hsp90ab1, and associated client proteins (AKT, p-AKT, ERK, p-ERK, and EGFR) were investigated in the malignant lymphoma cell lines Daudi and CA-46 using western blotting." (PMID 37719860, 2023). "The molecular docking and MMGBSA analysis of the compound DMBP against a panel of lymphoma-associated protein targets—AKT1, HSP90AA1, MTOR, MAPK1, and MDM2—revealed distinct binding affinities and interaction profiles, indicative of its potential as a multi-target therapeutic agent." (PMID 40699833, 2025). "The HPA database results showed that the protein levels of TSR1, WDR46, HSP90AA1, and NOP56 in lymphoma were higher than those in normal lymphoid tissue, whereas the protein level of UBC in lymphoma was lower than that in normal lymphoid tissue." (PMID 35263200, 2022).
oral cancer (4 papers, 2017 to 2024). "The ability of Jurkat cells to secret IFN-γ was enhanced after co-culture with HSP90AA1-knockdown oral cancer cells." (PMID 38713284, 2024). "Moreover, sEV derived from oral cancer cells contained a variety of HSPs, including HSP90α (HSP90AA1), HSP90β, TRAP1 (mitochondrial HSP90), HSP105, HSP70 (HSP72/HSPA1A and HSP70B’/HSPA6), GRP78/HSPA5 (ER chaperone), and HSC70." (PMID 32204513, 2020). "The clinical oncogenesis roles of HSP90AA1 and HSPA5 in oral cancer have been reported." (PMID 31222140, 2019). "Both Hsp90 (HSP90AA1; heat shock protein 90 kDa α (cytosolic), class A member 1) and Hsp110 (HSPH1; heat shock 105 kDa/110 kDa protein 1) were markedly reduced in miR-27a mimic-transfected oral cancer HSC-4 cells." (PMID 28708091, 2017).
acute kidney injury (3 papers, 2021 to 2025). Sudden and sustained deterioration of the kidney function characterized by decreased glomerular filtration rate, increased serum creatinine or oliguria. "A recent study has indicated that activating the HSP90AA1-Akt pathway can alleviate inflammation and apoptosis in an in vitro model of acute kidney injury." (PMID 38204223, 2025). "Five genes (CCT4, HSP90AA1, NCL, PABPC1, YBX1) were found to be associated with kidney disease, acute kidney injury, edema, tumor metastasis, transitional cell carcinoma, necrosis, and inflammation." (PMID 37058032, 2023). "CCT4, HSP90AA1, NCL, PABPC1, and YBX1 were found to be associated with kidney disease, acute kidney injury, edema, tumor metastasis, transitional cell carcinoma, necrosis, and inflammation." (PMID 37058032, 2023).
breast tumor (3 papers, 2021 to 2022). "It has been reported that elevated plasma HSP90AA1 levels are specific to malignant tumors and patients with metastatic liver or breast tumors have higher plasma HSP90AA1 levels than those without metastasis." (PMID 34109171, 2021). "Some studies believe that some HSP90 family genes such as HSP90AA1 and TRAP1 are not necessary for breast tumors to develop and metastasize; however, they have surprising regulatory effects." (PMID 34109171, 2021).
cholangiocarcinoma (3 papers, 2020 to 2025). A carcinoma that arises from the intrahepatic biliary tree (intrahepatic cholangiocarcinoma) or from the junction, or adjacent to the junction, of the right and left hepatic ducts (hilar cholangiocarcinoma). "Comparative transcriptome analysis using the cancer genome atlas (TCGA) data reveals a positive correlation between NANOG and HSP90AA1 mRNA levels in multiple human cancer types, such as cholangiocarcinoma, testicular germ cell tumors, uveal melanoma." (PMID 31992715, 2020). "Moreover, pan-cancer analyses reveal that HSP90AA1 contributes to pathways such as immune modulation and angiogenesis, further underscoring its relevance in cholangiocarcinoma biology." (PMID 41300430, 2025).
chronic kidney disease (3 papers, 2019 to 2026). Impairment of the renal function secondary to chronic kidney damage persisting for three or more months. "It suggests that HSP90AA1 facilitates vascular calcification in chronic kidney disease involving chaperone-mediated autophagy." (PMID 42072422, 2026). "This study shows that cell proliferation, differentiation, apoptosis, migration (SRC, HRAS, HSP90AA1, CDK2), and ameliorating chronic kidney disease (MAPK14, F2, LCK, MMP9) appear to play important roles in the therapeutic effect of SQW." (PMID 31275142, 2019).
Cognitive impairment (3 papers, 2025). Abnormal cognition is characterized by deficits in thinking, reasoning, or remembering. "HQH mitigates CYP-induced hippocampal neurotoxicity by decreasing oxidative stress, and inflammation, with HSP90AA1 being a key target, providing a novel therapeutic strategy for chemotherapy-associated cognitive impairment." (PMID 40970090, 2025).
head and neck cancer (3 papers, 2020 to 2025). A primary or metastatic malignant neoplasm affecting the head and neck. "Previous analysis illustrated that frequent mutations of HSPH1, HSPD1, HSPA4 and HSP90AA1 were detected in head and neck cancer in head and neck squamous carcinoma." (PMID 34712697, 2021).
liver fibrosis (3 papers, 2021 to 2024). "By mapping the candidate targets to the 66 known genes associated with hepatic fibrosis obtained from OMIM and DrugBank, 10 co-targets were found, including HSP90AA1, PPARG, MAPT, HSP90AB1, STAT1, and PPARA." (PMID 33510287, 2021). "Studies have found that HSP90AA1 exhibited anti-hepatic fibrosis effects in LX-2 cells (Chen CH." (PMID 35656312, 2022). "The key targets included 8 co-targets, including HSP90AA1, PPARG, HSP90AB1, STAT1, etc., which play pivotal roles in the pathogenesis of liver fibrosis." (PMID 33510287, 2021). "Our results demonstrated that SCST could target HSP90AA1, PPARG, HSP90AB1, STAT1, etc., further regulating the PPARG signalling pathway that is closely related to liver fibrosis, and the flavonoids and phenylpropanoids of SCST are important ingredients against hepatic fibrosis." (PMID 33510287, 2021). "Although STAT1 and HSP90AA1 have no direct targets, SCST indirectly affects PPARG, STAT1 and HSP90AA1 to exert anti-fibrosis effects through XDH, which is also closely related to liver fibrosis." (PMID 33510287, 2021).
myocardial ischemia (3 papers, 2016 to 2025). A disorder of cardiac function caused by insufficient blood flow to the muscle tissue of the heart. "Studies have shown that HSP90AA1 is significantly protective in myocardial ischemia–reperfusion injury." (PMID 38539069, 2024). "In this study, we hypothesized that Hsp90aa1 is a new target gene of miR-1 in cardiac ischemia/reperfusion injury." (PMID 27076094, 2016).
non-alcoholic fatty liver disease (3 papers, 2023 to 2025). "In non‐alcoholic fatty liver disease, USP14 stabilises HSP90AA1 through deubiquitination, leading to increased levels of CYP2E1 and further exacerbating disease progression." (PMID 40988122, 2025).